BRD4 (bromodomain containing 4)
Diseases named in the same sentence as BRD4 in open-access papers (continued):
Sharing a sentence is not in itself a finding about the gene and the disease.
lung carcinoma (continued). "Recent evidence has indicated that overexpression of the epigenetic reader bromodomain‐containing protein 4 (BRD4) contributes to a poor prognosis of lung cancers, and the suppression of its expression promotes cell apoptosis and leads to tumor shrinkage." (PMID 35988145, 2022). "In the present study, we demonstrated that inhibition of Bromodomain-containing protein 4 (BRD4) or genetic knock-down of BRD4, an epigenetic reader and master transcription coactivator, can sensitize lung cancer cells to TRAIL." (PMID 34400879, 2021). "Some studies have reported a transcriptional downregulation of c-Myc by JQ1 treatment by direct targeting of BRD4 in certain types of cancer, including lung cancer." (PMID 33858423, 2021). "Circ_0074027 induces invasion of lung cancer via activating bromodomain-containing protein 4 (BRD4) and MAPK-activating death domain-containing protein expression levels." (PMID 33628581, 2021). "Meanwhile, lung cancer cell activity was decreased after cotransfection of circDENND4C + si-BRD4 or circDENND4C + miR-141-3p at the same time." (PMID 34876902, 2021). "According to a previous study, p300/CBP‐associated factor (PCAF) mediated epithelial–mesenchymal transition (EMT) and promotes cancer metastasis by recruiting intestine‐specific homeobox (ISX) and bromodomain‐containing protein 4 (BRD4) in lung cancer." (PMID 34173348, 2021). "After transfection with silenced circDENND4C, the expression levels of circDENND4C, miR-141-3p, and BRD4 in lung cancer cells were detected by qRT-PCR." (PMID 34876902, 2021). "In this study, miR-141-3p in lung cancer tissues was reduced, thus showing an anticancer effect by targeting BRD4." (PMID 34876902, 2021). "Since the addition of sublethal concentrations of the BRD4 inhibitor enhanced the efficacy of CDK9 inhibitors on lung cancer cells, we next examined if the combination treatment showed any additive effect on the apoptotic pathway." (PMID 34359807, 2021). "We propose a potential strategy for combination-based therapy that employs CK2 inhibitors to potentiate the effects of BET inhibition in lung cancer cells by suppressing the phosphorylation of BRD4." (PMID 33712563, 2021). "In contrast, the numbers of invasive cells and cloned cells of lung cancer cells decreased after cotransfection of circDENND4C + si-BRD4 or circDENND4C + miR-141-3p." (PMID 34876902, 2021). "With this background in mind, the current study was performed to verify the expression of microRNA-608 and its potential target gene, namely bromodomain-containing protein 4 (BRD4), in lung cancer tissues and adjacent normal tissues." (PMID 31621555, 2020). "BRD4 was upregulated in the lung cancer tissues, while the inhibition of BRD4 by microRNA-608 mimics suppressed lung cancer cell proliferation, migration, and invasion." (PMID 31621555, 2020). "In other words, the migration and invasion abilities of lung cancer cells were dramatically restrained in the microRNA-608 mimics group, and this was partially abolished by the BRD4 overexpression." (PMID 31621555, 2020). "Brd4-regulated expression of stress proteins such as E-selectin and IL-8 was first demonstrated for lung cancer cells, but our studies were the first to link Brd4 to iNOS expression in glioblastoma cells." (PMID 33564720, 2020). "After confirming that BRD4 was the direct target of microRNA-608, the effect of microRNA-608 on lung cancer cell proliferation was investigated using a Cell Counting Kit 8 (CCK-8) assay." (PMID 31621555, 2020). "As the results exhibited, the expression level of BRD4 mRNA was highly elevated in the control group, compared to the lung cancer group (p < 0.01)." (PMID 31621555, 2020). "As BRD4 was revealed to be the direct target of microRNA-608, the expression level of BRD4 in lung cancer tissues and adjacent normal tissues was measured." (PMID 31621555, 2020).
lung carcinoma (continued). "The interaction between ISX, PCAF, and BRD4 was further evaluated in tumors and adjacent healthy lung tissues from patients with lung cancer." (PMID 31908141, 2020). "Our results indicate that high expression of microRNA-608 inhibits the proliferation, migration, and invasion of lung cancer cells by targeting BRD4 via the JAK2/STAT3 pathway." (PMID 31621555, 2020). "Accordingly, the lung cancer tissues had an elevated expression level of BRD4, in contrast to the adjacent normal tissues." (PMID 31621555, 2020). "Bromodomain-containing protein 4 (Brd4) maintains the constitutively active NF-κB in lung cancer cells by binding acetylated RelA." (PMID 27234396, 2013). "Increasing evidence has shown that BRD4 plays an important role in lung cancer development." (PMID 35988145, 2022). "Interestingly, BRD4 showed a strong positive correlation with KEAP1 expression in three major lung cancer subtypes, including LUAD, LUSC, and SCLC." (PMID 35453346, 2022). "Specific targets, such as PRMT1, KDM6B, CARM1, BRD4, and EZH2, have been shown to be associated with malignant phenotypes of lung cancer, influencing cell proliferation and metastatic processes (regulation of epithelial–mesenchymal transition and cell invasion)." (PMID 36233212, 2022). "Moreover, we confirmed that depletion of BRD4 suppressed the expression of c‐Myc and induced apoptosis in lung cancer." (PMID 35988145, 2022). "In this study, upregulated expression of BRD4 in lung cancer was detected by RT-qPCR." (PMID 34876902, 2021). "BRD4 and CDK7 are key factors for the function of epigenetic elements such as enhancers, and their inhibitors, JQ1 and THZ1, globally inhibit the expression of associated genes and suppressed lung cancer cell proliferation." (PMID 34001209, 2021). "In lung cancer tumor tissues, BRD4 and circDENND4C showed a coexpression positive correlation." (PMID 34876902, 2021). "After siRNA BRD4 was transfected into lung cancer cells, the expression of BRD4 was decreased." (PMID 34876902, 2021). "Wild‐type and mutant BRD4 were then transfected into lung cancer cells with ISX‐GFP (left)." (PMID 31908141, 2020). "Our study illustrated that microRNA-608 may restrain the abilities of proliferation, migration, and invasion of lung cancer cells by targeting BRD4 through the JAK2/STAT3 pathway." (PMID 31621555, 2020). "Based on the findings of the present study, it can be concluded that microRNA-608 may inhibit cell proliferation, migration, and invasion of lung cancer by targeting BRD4 through the JAK2/STAT3 pathway." (PMID 31621555, 2020). "And BRD4-activated NF-κB played the role in human kidney and lung carcinoma cells." (PMID 30455393, 2019). "We provide specific and previously undescribed data on fusions involving RAF1, ROS1, and BRD4 that suggest that existing drugs could be repurposed for use in rare pancreatic, breast, and lung cancers." (PMID 31097696, 2019). "The top 10 proteins (MIG6, GAPDH, NDRG1_pT346, BRD4, CD26, TFRC, INPP4B, GSK3ALPHABETA, IGFBP2, and DUSP4) were screened by applying the WBFS algorithm, and they can be regarded as the candidate biomarkers that are most closely associated with the classification of lung cancer subtypes." (PMID 37509950, 2023). "However, the role of BRD4 in lung cancer needs further research." (PMID 34876902, 2021). "Acetylation of intestine‐specific homeobox (ISX) and bromodomain‐containing protein 4 (BRD4) by PCAF promotes physical association and nuclear translocation of these proteins to drive epithelial–mesenchymal transition (EMT) through activation of EMT genes in lung cancer cells." (PMID 34112237, 2021). "Moreover, analysis of six lung cancer cell lines (A549, H358, H441, H1299, H1435, and H1437) revealed that the mRNA and protein expression patterns of ISX, PCAF, and BRD4 were co‐expressed in lung cancer cells relative to those in human diploid lung fibroblasts (WI38; Fig EV1D and E)." (PMID 31908141, 2020).
lung carcinoma (continued). "Thus, combinatorial therapies using MEK or BRD4 inhibitors together with NSD2 inhibition are likely to be needed to ensure a more comprehensive inhibition of oncogenic RAS-driven transcription programs in lung cancers with NSD2 overexpression." (PMID 27604143, 2016). "The study found six promising protein biomarkers that were directly correlated with the classification of lung cancer subtypes, including MIG6, NDRG1_pT346, BRD4, CD26, INPP4B, and DUSP4." (PMID 37509950, 2023). "In this study, pharmacologic inhibition and genetic silence of BRD2/BRD4 obviously downregulated GPX8 expression and prevented migration both in lung cancer cells and CAF." (PMID 35978854, 2022). "Of significance, the dBET6‐containing formulations suppressed lung cancer cell growth, as evaluated by Cell Counting Kit‐8 (CCK‐8) and colony formation assays, implying that the BRD4 degradation effectively inhibited the cancer cell growth." (PMID 35988145, 2022). "Consistently, we observed higher levels of BRD4 protein abundance in MV4-11 (AML) and MKN45 (gastric cancer) compared with A549 (lung cancer) and HepG2 (liver cancer) cells." (PMID 33820450, 2021). "METTL3 can promote the expression of multiple oncogenes such as BRD4, EGFR, TAZ, MAPKAPK2, and DNMT3A in human lung cancer cells." (PMID 34206803, 2021). "Four potential lysine acetylation sites on BRD4 [289 (AC2), 291(AC1), 329 (AC3), and 332 (AC4)] were developed and expressed to examine the impact of the ISX–BRD4 complex on EMT in lung cancer cells." (PMID 31908141, 2020). "The expression of both BRD4 (red) and PCAF (red) was co‐localized with ISX expression (green) in lung cancer cells (yellow arrow)." (PMID 31908141, 2020). "The testis-specific BET protein BRDT structurally resembles the ubiquitous BRD4 and is misexpressed in cancer, and we show that BRDT misexpression may affect lung cancer progression." (PMID 40085698, 2025). "Our results contribute insight into the transcriptional regulatory network of BRD4 and nominate new and effective combination therapy strategies in treating SCLC, a poorly differentiated neuroendocrine cancer, and the most malignant type of lung cancer." (PMID 35453346, 2022). "Furthermore, we found that BRD4 expression was positively correlated with KEAP1 expression and was predicted to be a factor binding to the KEAP1 promoter in lung cancer." (PMID 35453346, 2022). "In the analyzed cases of lung cancer, a high level of BRD4 was considered to be correlated with a poor prognosis of non-small cell lung cancer (NSCLC) and promotion of NSCLC proliferation, migration, and invasion." (PMID 31621555, 2020). "A study showed that JQ1 could disrupt the interactions between BRD4 and the acetylated lysine-310 residue on RelA, and inhibit the activation of TNF-α-mediated inflammatory cytokines in human lung cancer cells." (PMID 32303673, 2020). "As BRD2 and BRD4 were validated as the upstream regulators of GPX8, inhibition of GPX8 by bromodomain and extra‐terminal (BET) inhibitors may serve as a novel therapeutic potential for lung cancer metastasis." (PMID 35978854, 2022). "Therefore, in a similar manner to BRD4‐targeting inhibitors suppressing NSCLC growth, drugs targeting BRD3 could potentially treat lung cancer." (PMID 34605158, 2022). "Thus, BRD2 and BRD4 could regulate GPX8 expression and BET inhibitors may serve as a treatment strategy for GPX8‐driven lung cancer metastasis." (PMID 35978854, 2022). "In lung cancer tumor tissues, BRD4 showed a negative coexpression correlation with miR-141-3p." (PMID 34876902, 2021). "Hence, based on the western blot results, we predicted that the knockdown of BRD4 could decrease the expression level of CD44, jointly inhibiting the lung cancer cell migration and invasion." (PMID 31621555, 2020). "Therefore, we put forward the speculation that the knockdown of metastasis-related protein BRD4 could mediate the JAK2/STAT3 pathway and suppress the lung cancer cell migration and invasion." (PMID 31621555, 2020).
lung carcinoma (continued). "Nonetheless, a recent study utilizing a CRISPR screen found BRD2, rather than BRD3 or BRD4, promotes EMT in lung cancer models." (PMID 37461511, 2023).
colorectal cancer (45 papers, 2015 to 2025). A primary or metastatic malignant neoplasm that affects the colon or rectum. "Moreover, it has also been reported that upon loss of mediator kinase, MED12 and BRD4 cooperate to sustain colorectal cancer growth." (PMID 37953273, 2023). "Cytokine signaling leads to JAK2-dependent phosphorylation of Brd4 in colorectal cancer cells, thereby preventing Brd4 protein degradation by the ubiquitin proteasome system and enhancing the transcription of key oncogenic genes." (PMID 41009472, 2025). "ACP-1n inhibits BRD4 function in the nucleus of colorectal cancer cells by blocking LLPS to suppress SE-driven MYC expression." (PMID 40231263, 2025). "While IL6/IL8-JAK2 signaling was reported to induce BRD4 activation in colorectal cancer, leading to chromatin remodeling and resistance to BETi treatment." (PMID 38320998, 2024). "More importantly, the chemo‐regulation effects of DdLD NPs can inhibit colorectal cancer glycolysis to reduce the lactate production, and downregulate the PD‐L1 expression through BRD4 degradation." (PMID 38239040, 2024). "In colorectal cancer patients for whom high ACE2 plus high BRD4 expression is predictive of poor survival, pan-BET inhibition would need to consider proviral/antiviral actions of different BET proteins during SARS-CoV-2 infection." (PMID 36801948, 2023). "As a promising predictor in colorectal cancer diagnosis, exosomal circLPAR1 suppresses colorectal cancer development through decreasing BRD4 via METTL3-eIF3h interaction." (PMID 36814375, 2022). "We also demonstrated that the nucleoporin NUP210 was overexpressed and its expression was driven by BRD4, which regulated the proliferative ability and nuclear architecture of colorectal cancer cells." (PMID 35159127, 2022). "CircLPAR1 reduced BRD4 protein levels in colorectal cancer cells transfected with circLPAR1 lentiviral vector or incubated with circLPAR1-Exos compared with the NC/NC-Exos group." (PMID 35164758, 2022). "We next elucidated the functions of ACP-1n against cancer growth and its functional significance in the maintenance of CRC in vitro by targeting BRD4 and BRD4-driven gene expression in colorectal cancer HCT116 cells." (PMID 35159127, 2022). "Here, we show that cancer-associated fibroblast (CAF)-activated stromal signaling, interleukin-6/8-JAK2, induces BRD4 phosphorylation at tyrosine 97/98 in colorectal cancer, resulting in BRD4 stabilization due to interaction with the deubiquitinase UCHL3." (PMID 34290255, 2021). "The rIL6/8-induced BRD4 protein expression was also confirmed in several commercial colorectal cancer cell lines." (PMID 34290255, 2021). "MZ1 degrades BRD4 in colorectal cancer cell lines resistant to the BET degrader dBETi, which hijacks cereblon and not VHL." (PMID 36046113, 2021). "Then, we performed IHC staining in colorectal cancer patients, which also confirmed the higher expression of BRD4 in cancer tissues (P<0.001)." (PMID 31523195, 2019). "In this research, we examined the expression of BRD4 in colorectal cancer using TCGA database, which indicated BRD4 was overexpressed in colorectal cancer patients." (PMID 31523195, 2019). "BRD4 inhibition limited distal metastasis of colorectal cancer by regulating several key proteins including E-cadherin and Vimentin in the progression of EMT." (PMID 28545522, 2017). "We also report the success of using BRD4 inhibitor to target colorectal cancer cell growth in vivo, albeit through xenografts." (PMID 25603177, 2015). "In summary, our findings demonstrate that BRD4 is a positive regulator in colorectal cancer, playing a key role in tumor metastasis." (PMID 25603177, 2015). "In our present paper, we suggest that BRD4 has a role in colorectal cancer and epithelial-mesenchymal transition, in addition to the previous functions discovered." (PMID 25603177, 2015). "In this paper, we identify that BRD4 has an important role in colorectal cancer; and that its inhibition substantially wipes out tumor cells." (PMID 25603177, 2015).